DDTL (D-dopachrome tautomerase like)
Description:
May have a carboxy-lyase activity.
Synonyms: KB-226F1.2
Tractability: PROTAC: ubiquitination databases record sites on it.
Gene: Protein-coding gene on chromosome 22 (23,966,888 to 23,972,558, forward strand). Ensembl gene ENSG00000099974.
Subcellular location: Cytoplasm
Gene Ontology:
Molecular function: phenylpyruvate tautomerase activity
Cellular component: extracellular exosome; cytoplasm
Genetic constraint (gnomAD): Loss-of-function variants: 1 observed, 1.52 expected, observed/expected ratio (o/e) 0.66, 90% interval 0.21 to 1.83. That is too few expected variants to judge how well the gene tolerates losing a copy. Missense variants: 54 observed, 51.83 expected, observed/expected ratio (o/e) 1.04, 90% interval 0.84 to 1.31. Synonymous variants: 21 observed, 17.77 expected, observed/expected ratio (o/e) 1.18, 90% interval 0.84 to 1.68.
Homologues: Orthologues: chimpanzee DDTL (100% identical), dog DDT (63% identical), pig DDT (62% identical), macaque DDTL (59% identical), mouse Ddt (54% identical), tropical clawed frog ddt (48% identical), zebrafish ddt (40% identical). Paralogues in human: DDT (74% identical), MIF (28% identical).
Diseases named in the same sentence as DDTL in open-access papers:
DDTL is named in the same sentence as 4 diseases in open-access papers, as found by Europe PMC text mining. Sharing a sentence is not in itself a finding about the gene and the disease. The quoted sentences say what the papers report.
Alzheimer disease (1 paper, 2023). A progressive, neurodegenerative disease characterized by loss of function and death of nerve cells in several areas of the brain leading to loss of cognitive function such as memory and language. "More specifically, DDTL overexpression has been reported as possibly being involved in the pathology of Schizophrenia, while increased levels of ACYP have been detected in Alzheimer's disease patients’ fibroblasts." (PMID 36694130, 2023).
chronic obstructive pulmonary disease (1 paper, 2022). A chronic and progressive lung disorder characterized by the loss of elasticity of the bronchial tree and the air sacs, destruction of the air sacs wall, thickening of the bronchial wall, and mucous accumulation in the bronchial tree. "Our recent study showed that DDTL mRNA is produced in human lung tissue and that mRNA levels are not different between control lung tissue and lung tissue of patients with chronic obstructive pulmonary disease (COPD)." (PMID 35091838, 2022).
osteosarcoma (1 paper, 2022). A usually aggressive malignant bone-forming mesenchymal neoplasm, predominantly affecting adolescents and young adults. "To date, nothing is known about the biological function of DDTL or its expression in osteosarcoma." (PMID 35060345, 2022).
DDTL also shares sentences with these, for which no sentence is quoted: schizophrenia (1 paper).